SMAD6 (SMAD family member 6)
Diseases named in the same sentence as SMAD6 in open-access papers (continued):
Sharing a sentence is not in itself a finding about the gene and the disease.
epilepsy (1 paper, 2025). A brain disorder characterized by episodes of abnormally increased neuronal discharge resulting in transient episodes of sensory or motor neurological dysfunction, or psychic dysfunction. "Pathogenic variants in genes, such as PGAP3, CHD3, and SMAD6, can impair motor and cognitive performance without producing major neurological symptoms like epilepsy, suggesting that these deficits arise from developmental or structural abnormalities rather than from direct neurodegeneration." (PMID 41300846, 2025).
esophageal SCC (1 paper, 2010). "The favorable prognosis presented by Smad6+ oral SCC patients agrees with that described in 115 esophageal SCC using immunohistochemistry." (PMID 20462450, 2010).
gram-negative bacterial infections (1 paper, 2015). Infections caused by bacteria that show up as pink (negative) when treated by the gram-staining method. "SMAD6 downregulation during Gram-negative bacterial infection has been reported previously: the bacterial endotoxin LPS can inhibit the TGF-ß1 signaling pathway leading to SMAD6 expression." (PMID 26485688, 2015).
Hypercholesterolemia (1 paper, 2022). An increased concentration of cholesterol in the blood. "In a hypercholesterolemia-driven mouse model of CAVD, cholesterol-lowering strategies reduced calcification but not fibrosis or Smad2 signaling, and this effect was attributed to the selective down-regulation of Smad6." (PMID 36139812, 2022).
Insulin resistance (1 paper, 2021). Increased resistance towards insulin, that is, diminished effectiveness of insulin in reducing blood glucose levels. "Mechanism research reveals that NK-derived exosomal miR-1249-3p relieves insulin resistance and inflammation by targeting SKOR1, which interacts with SMAD6 and promotes glucose homeostasis by suppressing the TLR4/NF-κB signaling pathway." (PMID 34848693, 2021).
Intellectual disability (1 paper, 2022). "Notably, we did not identify any SMAD6 rare variants from four RUS patients with intellectual disability, and none of the SMAD6 mutant members of these 61 families has reached the point that an intelligence test is required." (PMID 34953066, 2022).
keratoconus (1 paper, 2017). A degenerative, structural disorder of the eye, characterized by a cone-shaped protrusion of the cornea. "An additional study demonstrated that some of the downstream messengers in the TGF-β axis may be abnormal in keratoconus: KC keratocyte cell lines had downregulated expression of SMAD6 and SMAD7 when compared to normal keratocyte cell lines." (PMID 28932341, 2017).
Kyphosis (1 paper, 2022). Exaggerated anterior convexity of the thoracic vertebral column. "Considering that the incidence of kyphosis or vertebral degeneration is high in the general population, we cannot define a definite association between the SMAD6 variant and kyphosis or vertebral degeneration at present." (PMID 34953066, 2022). "We have also observed that another seven SMAD6 mutant members in RUS families had kyphosis, (5/7 were less than 40‐years‐old) and six SMAD6 mutant members in RUS families had obvious vertebral degeneration." (PMID 34953066, 2022).
latent infection (1 paper, 2021). "Taken together, these data are consistent with the view that in order to support a latent infection, BMPR2 is required in order to express inhibitory SMAD6, which then prevents TGFbeta receptor signaling." (PMID 34061599, 2021).
Left bundle branch block (1 paper, 2024). A conduction block of the left branch of the bundle of His. "One previously GWAS-linked gene (SCN5A) and 3 novel genes (LMNA, SMAD6, HSPB9) were identified for atrioventricular and left bundle branch block (ICD10 code I44)." (PMID 38390584, 2024).
liver cancer (1 paper, 2018). An epithelial or non-epithelial malignant neoplasm that arises from the liver. "Since SMAD6 significantly promoted HCC cell proliferation and BRG1 upregulated the expression of SMAD6, we aimed to determine whether BRG1 promoted liver cancer cell proliferation through SMAD6." (PMID 29352111, 2018).
liver fibrosis (1 paper, 2025).
long bone fractures (1 paper, 2011). "A total of fifteen SNPs within four genes of the Bone Morphogenetic Protein (BMP) pathway (BMP-2, BMP-7, NOGGIN and SMAD6) were examined, in 109 randomly selected patients with long bone fractures as a result of motor vehicle accident, fall or direct blow." (PMID 21310029, 2011).
mantle cell lymphoma (1 paper, 2012). Mantle cell lymphoma is a rare form of malignant non-Hodgkin lymphoma affecting B lymphocytes in the lymph nodes in a region called the ``mantle zone''. "However, gene expression profiling data across NHL showed that Chronic lymphocytic leukemia (CLL) and Mantle cell lymphoma (MCL) had lower levels of SMAD6 and SMAD7, compared to the other B-cell malignancies." (PMID 23049692, 2012).
mesothelioma (1 paper, 2011). A usually malignant and aggressive neoplasm of the mesothelium which is often associated with exposure to asbestos. "We have analyzed a total of 4 genes: 2 genes that are up-regulated in H342-treated H2373 mesothelioma cells (Fos, JMJD7) and 2 genes that are down-regulated (SNIP1, SMAD6)." (PMID 21998702, 2011).
Myocardial fibrosis (1 paper, 2022). "The Smurf1/Smad6 complex antagonizes the myocardial fibrosis signal enhanced by TGF-β1/rock." (PMID 35034538, 2022).
myopia (1 paper, 2022). "On the one hand, the results of Metascape revealed a potential role of TF in the development of myopia with the enrichment of Smad6, NrOb2, Gtf2i, Tfap2a, Pax7, Pax6, Sox9 and Smad3." (PMID 34841657, 2022).
nasal polyp (1 paper, 2016). "Parallels may be drawn between the impact of VPA and TGF-β2 on Smad6 expression and the capacity of trichostatin A, also an HDAC inhibitor, to rescue TGF-β1-suppressed Smad7 in nasal polyp-derived fibroblasts." (PMID 26507880, 2016).
open-angle glaucoma (1 paper, 2022). Chronic outflow obstruction of the eye's drainage canals that can lead to increased internal eye pressure and optic nerve damage. "Moreover, most recently, 127 loci associated with open-angle glaucoma have been identified, with specific genes, such as RERE, VCAM1, ZNF638, SMAD6 potentially conferring open-angle glaucoma risk." (PMID 38983528, 2022).
osteosarcoma (1 paper, 2010). A usually aggressive malignant bone-forming mesenchymal neoplasm, predominantly affecting adolescents and young adults. "To establish that the effect of E2 on BMP-2-induced transcription was indeed mediated via the ERα, we examined the effects of E2 on BMP-2-induced Smad6 mRNA in the human osteoblast-like osteosarcoma cell line U2OS stably expressing doxycycline-inducible ERα." (PMID 19821774, 2010).
pancreatic ductal adenocarcinoma (1 paper, 2011). An infiltrating adenocarcinoma that arises from the epithelial cells of the pancreas. "Protein levels of all three Smads, Smad4, Smad6 and Smad7 were evaluated in paired normal pancreatic tissues and tumor samples of pancreatic ductal adenocarcinoma." (PMID 22195733, 2011). "This study investigates the differential protein expressions of Smad4, Smad6 and Smad7 in tumor as compared to normal tissue of pancreatic ductal adenocarcinoma (PDAC) and compares them with clinicopathological parameters and patient survival." (PMID 22195733, 2011). "In the present study, we examined the differential protein expressions of Smad4, Smad6 and Smad7 in surgically resected samples of paired tumor tissue of pancreatic ductal adenocarcinoma versus adjacent normal tissue." (PMID 22195733, 2011).
pilocytic astrocytoma (1 paper, 2025). Pilocytic astrocytoma is a rare subtype of low-grade glioma of the central nervous system characterized by a well circumscribed, often cystic, brain tumor with a discrete mural nodule and long, hair-like projections that extend from the neoplastic astrocytes.
pulp stones (1 paper, 2024). "However, polymorphic changes in the SMAD6 gene were linked to an increased risk of pulp stones." (PMID 39723289, 2024).
Sepsis (1 paper, 2015). Sepsis is defined as life-threatening organ dysfunction caused by a dysregulated host response to infection. "This study is the first report demonstrating the therapeutic potential of a Smad6-derived peptide (Smaducin-6) in sepsis treatment." (PMID 25766838, 2015). "Here, we demonstrate that this membrane-tethered Smad6-derived peptide, Smaducin-6, had therapeutic efficacy in mouse sepsis models: cecal-ligation–puncture (CLP)-induced and LPS-induced sepsis by inhibiting cytokine storm and apoptosis while enhancing neutrophil migration and bacterial clearance." (PMID 25766838, 2015).
skin cancer (1 paper, 2021). "Importantly, sulforaphane has been shown to attenuate a number of UVR-induced DMRs, e.g. within Notch1 and Smad6, in the mouse skin and reduce the incidence and multiplicity of skin cancer, in agreement with our early observations using broccoli extracts as delivery vehicles for sulforaphane." (PMID 34000624, 2021).
supravalvular aortic stenosis (1 paper, 2025). SupraValvar Aortic Stenosis (SVAS) is characterized by the narrowing of the aorta lumen (close to its origin) or other arteries (branch pulmonary arteries, coronary arteries). "One patient had bi-allelic SMAD6 variants, combined pulmonary valve defect and supravalvular aortic stenosis, craniosynostosis and radioulnar synostosis." (PMID 40133303, 2025).
tooth agenesis (1 paper, 2021). A tooth disease characterized by failure to develop one or more missing teeth. "In conclusion, genetic polymorphisms in BMP2 and SMAD6 were associated with isolated tooth agenesis." (PMID 34539446, 2021). "In conclusion, our study suggested that genetic polymorphisms in BMP2 and SMAD6 are involved in a higher chance to present isolated tooth agenesis." (PMID 34539446, 2021).
Tricuspid regurgitation (1 paper, 2022). Failure of the tricuspid valve to close sufficiently upon contraction of the right ventricle, causing blood to regurgitate (flow backward) into the right atrium. "In family R005, both the individuals I:1 and II:1 carried the same SMAD6 variant (c.1012G>t/p.E338X), I:1 was normal, but his son II:1 suffered from RUS and CHD (mild tricuspid regurgitation)." (PMID 34953066, 2022).
urothelial carcinoma of the bladder (1 paper, 2025). "Integrative analysis of multimodal sequencing datasets provided detailed insights into the molecular mechanisms mediating YTHDC1-dependent phenotypes and identified SMAD6 as a key transcript involved in the invasiveness of urothelial carcinoma of the bladder." (PMID 39741187, 2025).
ZIKV infection (1 paper, 2020). "Smaducin-6, a membrane-tethered Smad6-derived peptide, blocked Peli1-mediated NF-κB activation but did not have direct effects on ZIKV infection." (PMID 32544190, 2020).
tumor (31 papers, 2007 to 2025). "We showed a loss of expression of Smad6 in 28% tumor samples as compared to 8% loss in normal samples." (PMID 22195733, 2011). "Additionally, SMAD6 is associated with the tumor microenvironment, where high SMAD6 expression enhances immune-mediated tumor killing effects." (PMID 38767747, 2024). "Complete loss of Smad6 expression was seen only in 28%(7/25) of tumor cases." (PMID 22195733, 2011). "we extracted epithelial cells from eight tumor tissues and yielded that SMAD6 expressed in many epithelial cells." (PMID 38767747, 2024). "Nonetheless, in contrast to Ad-CMV-Tom-treated tumours, Ad-Smad6-treated tumours presented less variable CD31+ expression intensity across blood vessels and showed fewer (smaller) CD31 marker gaps." (PMID 39724753, 2024). "Among them, a positive correlation between the age of patients and the expression of Smad6 mRNA in the KC tumor (n = 33; R 0.509, p 0.013), including RCC (n = 29; R 0.521, p 0.019) was also found." (PMID 38085441, 2024). "Histologically, Ad-CMV-Tom- and Ad-Smad6-treated mice displayed similar tumor growth and morphological pattern." (PMID 39724753, 2024). "SMAD6 is known for its tumor suppressor role; its upregulation in cancerous tissue predicts a better prognosis." (PMID 38539520, 2024). "For the tumor promoter genes SMAD6, TERT, EGFR, and PIK3CA, low levels of expression were associated with better survival, as expected." (PMID 33919332, 2021). "Not only the mRNA levels but also the protein levels of SMAD6 in RB cell lines were notably higher than those in the non-tumor cell line." (PMID 31992960, 2020). "Functional experiments identified a key role for nuclear-Smad6 in promoting tumor sphere formation, proliferation and tumorigenesis of GBM cells." (PMID 29950561, 2018). "Forced expression of nuclear-Smad6 (Smad6-NLS, OE) significantly increased tumor sphere initiation and growth in A172 and T98G cells, whereas Smad6 KD significantly inhibited sphere formation in U87 and U251 cells." (PMID 29950561, 2018). "Here, we observed that SMAD6 promoted cell proliferation in HCC and BRG1 promoted tumour cell proliferation by upregulating the expression of SMAD6, at least partially." (PMID 29352111, 2018). "Collectively, this data would suggest that Smad6 has a role in cell-cell contact and communication, which affects tumour cell invasion." (PMID 27113436, 2016). "The second study, conducted on patient samples, contradicts this and demonstrates that the increased expressions of either Smad6 or Smad7 are infrequent in tumor compared to normal samples." (PMID 22195733, 2011). "Our study goes a step further, and shows that Smad6 as well as Smad7 are lost in tumor as compared to normal samples." (PMID 22195733, 2011). "The cytoplasmic staining of Smad6 and Smad7 in most samples implies that these two inhibitory Smads were in their activated states in most tumor samples." (PMID 22195733, 2011). "The difference in Smad6 protein levels in tumor tissue as compared to normal pancreatic tissue was highly significant by Fisher's exact test (p = 0.0015)." (PMID 22195733, 2011). "There was a significant difference in protein expressions of Smad4 (p = 0.0001), Smad6 (p = 0.0015) and Smad7 (p = 0.0005) protein in tumor as compared to paired normal samples." (PMID 22195733, 2011). "Moreover, although both Ad-CMV-Tom and Ad-Smad6 treated tumour exhibited a similar number of blood vessels per field, the percentage of blood vessels with endothelialised cells decreased nearly 3-fold in the Smad6-treated group when compared with controls." (PMID 39724753, 2024). "Interestingly, tumours treated with Ad-Smad6 also exhibited dense and expansive HLA-A+ tumour cells, which closely surrounded CD31+ blood vessels." (PMID 39724753, 2024). "Interestingly, eight among the overlapped hypermethylated genes (WT1, PAX6, GNAS, EPB41L1, CSMD1, CPEB1, RERG, and SMAD6) were previously reported to exhibit tumor suppressive functions." (PMID 34462486, 2021).
tumor (continued). "Interestingly, our ongoing study revealed that ectopic Smad6 is predominately expressed in cytoplasm and can act as a tumor suppressor in inhibiting migration, invasion, and metastasis." (PMID 29950561, 2018). "However, A good number (12/25, 48%) of tumor tissues showed moderate levels of Smad6 protein expression, in contrast to Smad4 where most of the cases were weakly positive or absent." (PMID 22195733, 2011). "Since TGF-β signals may function in potent tumor suppression in normal epithelial cells and in early-stage tumors, we speculated that genetic variations in SMAD6 may result in altered gene expression or regulation of signaling function." (PMID 21984931, 2011). "However, SMAD6 was downregulated in patients with deeper tumor infiltration." (PMID 33193701, 2020). "Taken together, these data demonstrate that YTHDC1 regulates SMAD6 expression in UCB in a m6A-dependent manner and thus reveal a mechanism through which downregulation of an epitranscriptomic reader can promote tumor invasiveness." (PMID 39741187, 2025). "Ex vivo analysis of labelled primary tumours revealed similar Gaussia luciferase activity between Ad-CMV-Tom and Ad-Smad6 groups, which were significantly higher than background control brain luciferase readings." (PMID 39724753, 2024). "At day 9 post-tumour implantation, mice were intracranially treated with either control adenovirus (Ad-CMV-Tom) or adenoviruses targeting TGF-β signaling activity (Ad-Smad6 or Ad-Smad7)." (PMID 39724753, 2024). "SMAD6 can also regulate TGF-β signaling pathway, which is conducive to tumor growth, spread, and metastasis." (PMID 36969909, 2023). "To verify the function of the lncFGD5-AS1/miR-196a-5p/SMAD6/BMP axis in vivo, we employed western blot and QRT-PCR in harvested tumor tissue." (PMID 33892661, 2021). "SMAD6 of the TGF-B signaling pathway has also been found to be hypermethylated in RCC, which can activate the TGF-B pathway and promote tumor proliferation." (PMID 33052225, 2020). "RHOA, SMAD2, SMAD4, SMAD5, SMAD6, BMPR1A, SMAD7 and MYC-, which thereby emerge as candidate genes to play an important role in CRC tumor metastasis." (PMID 27662660, 2016). "Using this approach, 7 genes were identified as undergoing tumor-specific aberrant promoter methylation in HCC, including IFITM1, SMAD6, TBX15, CHST4, and LRRC4 with hyper-methylated promoters and CCL20 and NQO1 with hypo-methylated promoters." (PMID 26300991, 2015). "In further experiments, we identified tumor areas in UCB tissue sections via H&E staining and then used simultaneous RNA fluorescence in situ hybridization (FISH) and immunofluorescence (IF) to detect SMAD6 mRNA and YTHDC1 protein, respectively." (PMID 39741187, 2025). "Moreover, keeping in mind the inhibitory effect of Smad6 on the activity of the TGFβ system, it could be discussed, whether the observed positive correlation between the age of KC patients and the expression of Smad6 mRNA in tumor contribute to a slower course of cancer disease in the elderly." (PMID 38085441, 2024). "The results revealed a negative correlation between SMAD6 and tumor-infiltrating macrophages." (PMID 38767747, 2024). "We found that 7 genes (IFITM1, SMAD6, TBX15, CHST4, LRRC4, CCL20, and NQO1) showed significantly different promoter methylation levels between tumor and non-tumor tissue (P value < 0.001) in approximately 80 % of the 78 HCCs." (PMID 26300991, 2015).